TOMM22 (translocase of outer mitochondrial membrane 22)
Description:
Central receptor component of the translocase of the outer membrane of mitochondria (TOM) complex essential for the recognition and translocation of cytosolically synthesized mitochondrial preproteins. Together with the peripheral receptor TOMM20, functions as the transit peptide receptor and facilitates the movement of preproteins into the translocation pore. The TOM complex associates with the ion channel VDAC2 and PINK1 kinase at depolarized mitochondria, this interaction stabilizes PINK1 at the outer mitochondrial membrane and triggers downstream mitophagy by the recruitment of the E3 ubiquitin ligase PRKN. Required for the translocation across the mitochondrial outer membrane of cytochrome P450 monooxygenases (By similarity).
Synonyms: TOM22; 1C9-2; MST065; MSTP065
Tractability: Small molecule: a structure with a bound ligand is known. Antibody: UniProt predicts a signal peptide or a membrane-spanning region. PROTAC: ubiquitination databases record sites on it; its protein half-life has been measured.
Gene: Protein-coding gene on chromosome 22 (38,681,924 to 38,685,421, forward strand). Ensembl gene ENSG00000100216.
Subcellular location: Mitochondrion outer membrane
Subcellular location (Human Protein Atlas): Mitochondria
Pathways (Reactome):
Autophagy: PINK1-PRKN Mediated Mitophagy
Protein localization: Mitochondrial protein import
Gene Ontology:
Molecular function: protein binding; protein transmembrane transporter activity
Biological process: protein import into mitochondrial matrix; protein insertion into mitochondrial outer membrane; protein localization to mitochondrion; intracellular protein transport
Cellular component: membrane; mitochondrial outer membrane; mitochondrial outer membrane translocase complex; mitochondrion; TOM complex
Genetic constraint (gnomAD): Loss-of-function variants: 3 observed, 16.93 expected, observed/expected ratio (o/e) 0.18, 90% interval 0.08 to 0.46. The upper end of that interval is the gene's LOEUF score, 0.46, which puts it in group 2 of 6, group 1 being the genes least tolerant of losing a copy. Missense variants: 159 observed, 187.34 expected, observed/expected ratio (o/e) 0.85, 90% interval 0.75 to 0.97. Synonymous variants: 91 observed, 78.05 expected, observed/expected ratio (o/e) 1.17, 90% interval 0.98 to 1.39.
Homologues: Orthologues: chimpanzee TOMM22 (100% identical), macaque TOMM22 (100% identical), guinea pig TOMM22 (96% identical), dog TOMM22 (95% identical), mouse Tomm22 (94% identical), pig TOMM22 (94% identical), rat Tomm22 (94% identical), tropical clawed frog tomm22 (64% identical), zebrafish tomm22 (63% identical), Drosophila melanogaster mge (42% identical), Caenorhabditis elegans tomm-22 (27% identical).
Diseases named in the same sentence as TOMM22 in open-access papers:
TOMM22 is named in the same sentence as 15 diseases in open-access papers, as found by Europe PMC text mining. Sharing a sentence is not in itself a finding about the gene and the disease. The quoted sentences say what the papers report.
myopia (1 paper, 2022). "Although abnormal mitochondrial function has been reported during myopia progression, amyloid β (Aβ) peptides and TOMM22 have not been previously implicated." (PMID 35153787, 2022).
pancreatic cancer (1 paper, 2025). "Recently, one study revealed that TOMM22 overexpression promotes aggressive cell growth in in pancreatic cancer by modulating mitochondrial protein import and function, suggesting its potential as an early diagnostic/prognostic biomarker." (PMID 41433368, 2025).
Pruritus (1 paper, 2024). Pruritus is an itch or a sensation that makes a person want to scratch. "Tomm22 protein, a core component of the mitochondria outer membrane protein translocation pore, is the human TOM complex and the proapoptotic protein Bax receptors, that has been found upregulated in all pruritus groups." (PMID 38577622, 2024).
tumor (7 papers, 2019 to 2025). "However, there is no previous study investigating the role of MFN1 and TOMM22 in the progression of CRC, we are the first study revealing the tumor suppressor role of these two genes, Especially TOMM22 which was overexpressed in the tumor samples." (PMID 36333388, 2022).
infection (3 papers, 2017 to 2025). The state of being infected such as from the introduction of a foreign agent such as serum, vaccine, antigenic substance or organism. "The results demonstrated that TOMM22 expression progressively increased over time and with increasing infection dosage, parallelling the expression trend of LINC02528 during Mtb infection." (PMID 41433368, 2025). "The Spike infection decreased NAD+-dependent protein deacetylases 3, SIRT3, that maintains mitochondrial metabolic activity (0.59-fold in Spike vs VSV-G, P = 0.0031) and translocase of the outer membrane of mitochondria, TOMM22, gene expression (0.73-fold in Spike vs VSV-G, P = 0.0229)." (PMID 37504520, 2023).
TOMM22 also shares sentences with these, for which no sentence is quoted: cancer (2 papers); Listeria infection (2); diabetes (1); hepatoblastoma (1); Hyperglycemia (1); Influenza Infection (1); ischemic heart disease (1); myopathy (1); pulmonary tuberculosis (1); Sepsis (1).